VIM (vimentin)
Diseases named in the same sentence as VIM in open-access papers (continued):
Sharing a sentence is not in itself a finding about the gene and the disease.
tumor (continued). "Immunohistochemistry was used to detect the protein expression levels of vimentin, CD34, Ki-67 and E-cadherin in transplanted tumor tissues." (PMID 26871290, 2016). "In this study, CXCL1 significantly activated the EMT pathway by upregulating the expression of E-cadherin, N-cadherin, and Vimentin in HCC cells and enhanced tumor cell invasion capacity, while reducing CXCL1 expression inhibited these processes." (PMID 27542259, 2016). "Having the vimentin and CD56 tumor cell stainings as a reference, fewer of the invasive compared to the central tumor cells expressed Ki-67." (PMID 27454178, 2016). "Vimentin is mainly found in the stroma and CD44 is also found in the tumor stroma, with increased expression close to the tumor epithelium." (PMID 27590006, 2016). "It is concluded that use of immunostaining of cellular antigens like Vimentin, S100, EMA, CEA, GCDFP 15, CD10, p63, CD34, pan-cytokeratin (AE1/AE3), CK5, CK6, and CK7 is helpful in diagnosing such tumours." (PMID 27034895, 2016). "On Immunohistochemical staining, the tumor cells were positive for CD32, CD34, Vimentin and smooth muscle actin." (PMID 26739818, 2016). "The combination of IHC tests including LCA, vimentin, desmin and CD99 is useful to primarily assess the phenotype of the tumor cells." (PMID 27756397, 2016). "In our study, we evaluated ccRCC tumor tissues by immunofluorescence staining of common EMT markers (CDH1, CK18, CK19, VIM, S100A4) and stratified patients to EMT positive and EMT negative groups." (PMID 27549611, 2016). "IHC analysis of tumor sections also revealed that HapT1tumors contained myofibroblast-like cells, which is based on the fact that they stained positive for α-SMA and vimentin." (PMID 27259232, 2016). "Immunohistochemistry showed that IR-induced IL-4 increased the expression of major components related to p-Stat6, mesenchymal trait marker, Vimentin; invasiveness marker, MMP-9; stemness maintenance marker, Sox2; and tumor proliferation marker, Ki-67." (PMID 27895317, 2016). "Two of the hallmarks of tumor cells which have undergone EMT are the downregulation of the epithelial surface protein E-cadherin which control cell-cell contact and increase in vimentin expression." (PMID 27533087, 2016). "Although isolated from the same tumor sample, SW13- and SW13+ subtypes have distinct cellular morphology and actin cytoskeletal structures in addition to the absence or presence of a vimentin intermediate filament network." (PMID 27188282, 2016). "Human vimentin staining demonstrated that vimentin expression in Vim k/d tumor is significantly less than in control tumors, demonstrating that the Vim k/d CAG cells kept the vimentin-k/d phenotype in vivo." (PMID 26849235, 2016). "Immunohistochemically, an adenomatoid tumor is positive for markers, such as CK (AE1/AE3) ΕMΑ, Cam5.2, CK 5/6, CK7, calretinin, vimentin, WT1, and HBME-1." (PMID 28003830, 2016). "Paraffin-embedded tumour tissue from two cohorts (N=103 and 245) of primary VSCCs were stained for L1CAM, vimentin and E-cadherin." (PMID 27028855, 2016). "When 14-3-3ζ was down-regulated in tumor cells, E-cadherin protein was up-regulated, and Vimentin and snail were down-regulated, suggesting a potential role for 14-3-3ζ in EMT of tumor cells." (PMID 26910835, 2016). "The tumour cells displayed widespread and strong positivity for CEA and the outer layers of cells were positive for S-100 and Vimentin." (PMID 27034895, 2016). "The β-catenin, N-cadherin, Vimentin, Snail, and Twist levels of expression were greater in HOTAIR-overexpressing tumours compared with the control tumours." (PMID 27323817, 2016). "Previous studies have shown that Gal-DOX/siRNA-L inhibited tumor growth by combined effect of DOX and vimentin siRNA than single delivery of either DOX or vimentin siRNA." (PMID 28335269, 2016).
tumor (continued). "We propose that ANG2 can induce abnormal EMT by regulating E-cadherin, Snail, Twist and vimentin, and affect VEGF expression, thus resulting in angiogenesis and tumor metastasis." (PMID 27492854, 2016). "MED30 induced the expressions of EMT-related genes (N-cadherin; CDH2, P-cadherin; CDH3, twist related protein 1 and 2; TWIST1/2, vimentin; VIM), but inhibited the expression of E-cadherin (CDH1) a known tumor suppressor." (PMID 26110885, 2015). "The tumor was immunonegative for GFAP, creatine kinase, Syn and B-cell lymphoma 2; however, it was immunopositive for vimentin, EMA, S-100 and TTF-1." (PMID 25777996, 2015). "In tumor-adjacent normal breast tissues, the expressions of CTGF were also examined to positively correlate with FN1 and VIM and negatively correlate with CDH1." (PMID 26318291, 2015). "IL–20 induced the expression of N-cadherin, STAT3, vimentin, fibronectin, RANKL, cathepsin G, and cathepsin K, all of which are involved in cancer cell migration, EMT, and tumor-induced osteolysis." (PMID 26440411, 2015). "Results from IHC staining further revealed that tumor samples generated with IWP2-treated AMSCs-co-cultured HCT116 cells expressed more abundant E-cadherin and less vimentin proteins, as compared with the untreated AMSCs-co-cultured HCT116 cells." (PMID 26060426, 2015). "Proteomic analysis of MDCKYBX1 tumour xenografts revealed 428 proteins identified in MDCKYBX1 tumour xenografts, and EMT markers (VIM, FN1 and S100A4) and proteins involved in cancer progression (H-Ras and CLU) were identified." (PMID 25980435, 2015). "Vimentin IHC demonstrated analogous features to the GBM 12055 model, with dense tumor growth within the injected striatum and infiltrative growth along myelinated fiber tracts in the contralateral hemisphere." (PMID 26517124, 2015). "With the mechanical modulations generated by vimentin, the EMT-related cancer cells became increasingly organized to resist various stresses generated by the tumor microenvironment, and thus increased in malignancy." (PMID 25965826, 2015). "Immunohistochemically, the tumor cells were positive for CK7, α-methyl-acyl-CoA racemase (AMACR), CA19-9, vimentin, PAX8, PAX2, CD138 and CD10, and negative for p63 and prostate specific protein (PSA)." (PMID 26428868, 2015). "Moreover, our finding of circulating cells with positive vimentin expression supports the contention that EpCAM-based CTC isolation may underestimate the number of neoplastic elements likely delivered from primitive tumor to the blood stream." (PMID 26571236, 2015). "Given that MMPs and EMT were involved in tumor cells metastasis, we further investigated the link between HDAC4 expression and E-cadherin, Vimentin, MMP2 and MMP9 expression." (PMID 26441331, 2015). "Immunohistochemical staining showed that vimentin and SMA were positively expressed in these tumor cells, while desmin was only partially expressed; in contrast, no sign of S-100 or CD34 protein expression was found in these spindle-shaped tumor cells." (PMID 26303928, 2015). "The tumor cells show diffuse strong expression of Factor VIII, Fli-1, INI-1, vimentin, MDM2, and CDK4, local expression of CD31, AE1/AE3, EMA and P63, and no expression of CD34, S-100, actin-sm, desmin, MyoD1, and HMB45." (PMID 26315812, 2015). "Decreased E-cadherin and increased vimentin are indicative of epithelial-mesenchymal transition (EMT) in cancer, and elevated E-cadherin suppresses tumor invasion." (PMID 26068949, 2015). "Compared to non-specific RNA interference, knockdown of TIP30 significantly enhanced the growth and invasion of tumor cells Furthermore, H&E staining and IHC staining for TIP30, Vimentin and E-cadherin were performed on tumor sections." (PMID 25544767, 2015). "E-cadherin exhibited low expression, whereas vimentin, MMP-2, and MMP-9 exhibited high expression in tumor cells treated with doxycycline compared with the untreated group in both the membrane and cytoplasm." (PMID 26512779, 2015).
tumor (continued). "Immunohistochemically, the tumor revealed strong and diffuse staining for CD34, bcl-2, and vimentin, and a high mitotic index (seven mitoses per 10 high-power fields)." (PMID 25649645, 2015). "Immunohistochemical staining showed strong expression of vimentin and smooth muscle actin (SMA) in the tumor cells, while desmin was only partially expressed; however, no sign of S-100 protein or CD34 expression was found in these cells." (PMID 26303928, 2015). "The inhibition of E-Cadherin and induction of Vimentin are considered established markers of EMT and tumor progression." (PMID 26157476, 2015). "We employed a range of antibodies to characterize the immunophenotype of the tumor cells and found that the tumor cells were positive for CD34, CD99, bcl-2, and vimentin." (PMID 25688313, 2015). "Immunohistochemical staining shows that most tumour cells are positive for MIB-1, vimentin, EMA, WT-1, and CD57; in contrast, CK7 staining exhibits weak focal positivity." (PMID 25907695, 2015). "In our case, immunohistochemistry revealed that the tumor cells were positive for α-SMA, desmin, and vimentin." (PMID 26380169, 2015). "The data demonstrate that vimentin is predominantly expressed in mesenchymal cells, which were around NCI-N87 xenograft tumor tissues." (PMID 25669984, 2015). "Expression levels of the representative mesenchymal markers, vimentin and ZEB1, are increased, while expression of the epithelial marker E-cadherin was decreased in AR tumors compared to Br3CT tumor." (PMID 26336988, 2015). "Immunohistochemistry of the tumors showed a marked positivity for Vimentin and low positivity to S100 protein, cytokeratin E1 to E3 and MSA that is compatible with the tumor described." (PMID 26493452, 2015). "Results revealed a significantly lower expression of Vimentin, CD44 and ALDH1 and a higher expression of E-cadherin in tumor tissues generated from the IshikawashPiwil1 cells compared with IshikawaNT cells." (PMID 26506848, 2015). "Immunohistochemical staining showed that most tumour cells were positive for WT-1, CD57, MIB-1, Vimentin, and EMA, while CK7 staining showed weak focal positivity." (PMID 25907695, 2015). "Performed immunohistochemical studies showed strong reactivity for smooth muscle actin (SMA) within 100% of the tumor cells, reactivity for HMB-45 (within 30-40% of the tumor cells and vimentin." (PMID 25896860, 2015). "The molecular phenotype of RCC within the scaffolds was assessed by immunohistochemistry for cytokeratin, vimentin, and RCC antigen and compared with expression in the corresponding tumor or non-tumor specimens from which cells were derived." (PMID 26317980, 2015). "On immunostaining, the tumor cells were positive of CD10, CD56, β-catenin, and progesterone receptor as well asα1-antitrypsin and vimentin." (PMID 26599966, 2015). "In this study, we found that AOC4P downregulated vimentin expression, thereby reducing HCC tumor growth and metastasis." (PMID 26160837, 2015). "Both EMT (E‐cadherin,vimentin) and CS (CD133, CD44, aldehyde dehydrogenase) markers were analyzed through immunostaining of tumor specimens." (PMID 26471868, 2015). "The intraoperative assessment revealed that the tumor had a rich blood supply and the SCO tumors were immunopositive for vimentin, S-100, EMA and TTF-1." (PMID 25777996, 2015). "This study provided new insight into vimentin for EMT-related cancer mechanotransduction and tumor malignancy." (PMID 25965826, 2015). "At these sites of intense interaction, the tumor cells in the protrusion had undergone EMT, and were expressing vimentin." (PMID 26375443, 2015). "The vimentin- and Ki-67-stained cells in the mouse KCI-MENG1-LPSX tissue were markedly more abundant and more intensely stained than in the original KCI-MENG1 tumor." (PMID 26174772, 2015). "Immunohistochemistry demonstrated that the tumor cells were positive for α-smooth muscle actin (α-SMA), desmin, and vimentin." (PMID 26380169, 2015).
tumor (continued). "The tumor cells were positive for tumor cell glial fibrillary acidic protein (GFAP), S-100 protein, vimentin, human leukocyte differentiation antigen 34 (CD34), epithelial membrane antigen (EMA), cluster of differentiation 99 (CD99) and D2-40." (PMID 24348765, 2014). "Wif-1 appeared to be the most sensitive marker of advanced neoplasia in either urine or serum samples (52% and 29%) compared to ALX-4 and Vimentin (23% and 15% vs. 4% and 8%, respectively)." (PMID 25025467, 2014). "Immunohistochemical findings showed that the tumor cells in all four cases were positive for AMACR, CK, CK7, CK19, EMA, HMWK, E-cadherin, and vimentin." (PMID 25476569, 2014). "Complete excision of the tumor with lymph node sampling was done and final HPE was consistent with CCSK with positive ipsilateral hilar lymph nodes (Stage 3); IHC was positive for vimentin." (PMID 25374799, 2014). "The tumor cells of all four cases were positive for CD31, F8 and vimentin; CD34 expression was positive in three cases; and EMA was focally positive in one case." (PMID 25364420, 2014). "The immunohistochemical profile of the current tumor is comparable to previously reported TLFCK cases (AE1/AE3+, CK7+, PAX-2+, PAX-8+, vimentin+, EMA+, TTF-1−, TG−, CD56−, WT-1−, CD10−, and CEA−)." (PMID 25133003, 2014). "In our study, we selected four masks: tumor (cytokeratin+), stromal (vimentin+), tumor nuclei (DAPI+/cytokeratin+) and tumor cytoplasm (DAPI-/cytokeratin+)." (PMID 24988459, 2014). "Untreated high density mono-cultures of HCT116 expressed vimentin at markedly lower levels and higher E-cadherin expression compared to HCT116 high density tumor microenvironment co-cultures." (PMID 25238234, 2014). "Immunofluorescence staining of the On-chip Sort sorted cells identified these cells as nuclei, CK and/or vimentin-positive and CD45-negative under the fluorescent microscope, confirming these cells to be tumor cells." (PMID 24886394, 2014). "This was supported by the inverse correlation between E-cadherin and IL-6 expression, positive correlation between IL-6 and vimentin mRNA expression and between STAT3 phosphorylation and IL-6 expression in tumor tissues." (PMID 24789104, 2014). "Our results in this study show that tumor microenvironment co-culture increased EMT markers, such as vimentin, slug and decreased E-cadherin in HCT116 cells compared to mono-cultures, indicating the high density tumor microenvironment co-cultures induces EMT." (PMID 25238234, 2014). "Once this process is under way in a tumor, it is typical to find a coordinated alteration in the expression of all these genes: the expression of ZEB1, ZEB2, VIM, and SNAI1 is upregulated, while the expression of CDH1 is downregulated." (PMID 25157365, 2014). "We found that the expression levels of fibronectin, vimentin, N-cadherin and SNAIL were decreased but the expression of E-cadherin was increased in the NRP1-depleted tumor cells." (PMID 24736504, 2014). "Meanwhile, over-expression of WIF1 dramatically reduces tumor growth in a xenograft mouse model, accompanied by an increased E-cadherin and CK18 expression and a decreased vimentin level in tumor tissues." (PMID 24618337, 2014). "High expression of FoxP3, vimentin and L1CAM in PDAC cells as well as a tumor-related localization of macrophages each tended to correlate with higher tumor grade." (PMID 24797069, 2014). "Immunohistochemical assay demonstrated that the tumor cells of MTSC and sPRCC were positive for AMACR, CK, CK7, CK19, EMA, HMWK, E-cadherin, vimentin and Ki - 67 index was <5%." (PMID 25476569, 2014). "In our study, we selected two alternative mask pairs: tumor (cytokeratin) and macrophage (CD68+) for the HGF analysis and tumor (cytokeratin) and stroma (vimentin+) for the c-Met analysis." (PMID 24952592, 2014).
tumor (continued). "Immunohistochemically, tumor cells were positive for cytokeratin, epithelial membrane antigen (EMA), and vimentin so that the histopathological diagnosis was compatible with biphasic spindle cell type SS in the lung." (PMID 25152824, 2014). "MiR-30c was previously reported to play a suppression role in tumour cell proliferation, metastasis and drug resistance by targeting BCL9, TWF1, vimentin and KRAS." (PMID 24595016, 2014). "Immunohistochemistry (IHC) is the preferred diagnostic tool, by which distinctive small, uniform and round tumor cells surrounding capillaries can be found, which are strongly positive for SMA, vimentin, calponin, collagen type IV and laminin." (PMID 24932234, 2014). "Under immunohistochemical examination, the tumor is positive for several neural markers, such as NSE, CD99, and vimentin." (PMID 25404964, 2014). "On immunohistochemistry, the tumour cells were positive for epithelial membrane antigen (EMA), cytokeratin, and vimentin." (PMID 25243090, 2014). "Immunohistochemical staining of the tumour revealed that the tumour cells were positive for the epithelial membrane antigen (EMA), cytokeratin 18 (CK18), and vimentin." (PMID 24587922, 2014). "Immunohistochemical staining revealed that the tumor cells were positive for AE1/AE3, cytokeratin (CK) 7, vimentin, cluster of differentiation (CD) 31 and E-cadherin, but showed no staining for CD10, CD34, factor VIII, CK20, carcinoembryonic antigen or desmin." (PMID 25120677, 2014). "Upon immunohistochemical staining of the primary and metastatic tumors, the tumor cells were found to be positive for epithelial membrane antigen (EMA), cytokeratin and vimentin." (PMID 24765153, 2014). "Elevated levels of VIM and SLUG have been also shown to be correlated with the EMT process; and also to poorer prognosis and tumour recurrence." (PMID 25266665, 2014). "Of interest, taxanes-resistant cells display hallmarks of mesenchymal phenotype, including increased vimentin expression; its aberrant expression during EMT is suggested to be an essential element for epithelial plasticity and tumor cell metastasis." (PMID 24632568, 2014). "Immunohistochemical staining of the tumor cells confirmed strong membranous expression of CD99 and focal expressions of vimentin and synaptophysin." (PMID 23537038, 2013). "The MMTV-PyVT/HdhQ111/Q111 tumours had lower levels of the tight junction protein zonula occludens 1 (ZO1), E-cadherin and β-catenin, and an increased level of the mesenchymal marker vimentin compared to MMTV-PyVT/HdhQ7/Q7 tumours." (PMID 23300147, 2013). "Tumor cells strongly expressed CD63, vimentin, and NKI-C3, while desmin, smooth muscle actin (SMA), S100, CK7, CK20, CK5/6, epithelial membrane antigen (EMA), P63, CD1a, and MART-1 were all negative." (PMID 23691398, 2013). "EMT changes further increased the mesenchymal characteristics of this tumor as discerned by the decrease in E-cadherin and the increase in ZEB1 and vimentin." (PMID 24403226, 2013). "Immunohistochemical studies show strong staining of the tumor cells with CD34, Bcl-2, CD99, and vimentin." (PMID 23662242, 2013). "Given that MMP2, MMP9, vimentin, and ZEB1 were regarded as potential elemental genes implying the pro-metastatic state and higher malignancy of tumor cells, as well as E2F1 downstream target genes, RT-PCR was performed to detect changes in mRNA levels." (PMID 24023875, 2013). "Vimentin expression has been shown to be transactivated by β-catenin/TCF and thus increasing the tumor cell invasive potential." (PMID 23785295, 2013).